AURKA (aurora kinase A)
Diseases named in the same sentence as AURKA in open-access papers (continued):
Sharing a sentence is not in itself a finding about the gene and the disease.
tumor (continued). "In terms of immune microenvironment, we found that the expressions of AURKA, CCNA2, CCNE1, CDK1, CHEK1, and PLK1 were negatively correlated with tumor immune infiltrating cells." (PMID 36483630, 2022). "In summary, our work identifies m6A reader YTHDC1 as the fulcrum of tumor suppressor RBM4 oncogenic switch and reveals a previously unappreciated role of nuclear AURKA in regulating RNA splicing." (PMID 35361747, 2022). "Cell cycle-related genes such as AURKA, AURKB, GTSE1, CCNA2, and MYBL2 were shown to promote tumor progression of LUAD." (PMID 36304306, 2022). "AURKA interferes with the YTHDC1-SRSF3 complex, thus inhibiting the production of tumor-suppressing isoform RBM4-FL." (PMID 35361747, 2022). "In particular, most of the amplified genes are involved in proliferation and tumour progression in PDAC, such as AURKA, HRH3, MIR646, MRGBP, PCK1, PMEPA1, SLCO4A1-AS1, SOX18, and TNFRSF6B." (PMID 36289850, 2022). "Inhibition of both Aurora kinase A (AURKA) and poly (ADP-ribose) polymerase (PARP) in preclinical models of DDR-defective NEPC was also able to suppress tumor growth." (PMID 36358940, 2022). "The results demonstrated that overexpression of AURKA promoted tumour progression, while SIN1 knockdown attenuated AURKA-elicited malignant phenotype changes in vivo." (PMID 36471438, 2022). "AURKA and HDM2 have been found to be overexpressed in GC cells in about half of the primary GC tumours." (PMID 36615513, 2022). "Mechanically, POLE2 knockdown promoted the ubiquitination as well as reduced the stability of Forkhead transcription factor (FOXM1), which is a known tumor promotor in GBM, through Aurora kinase A (AURKA)." (PMID 35039475, 2022). "Aurora-A kinase (AURKA) functionally regulates cell mitosis and is closely related to the occurrence and development of a variety of tumours." (PMID 36471438, 2022). "The results of immunohistochemistry showed that protein expression levels of AURKA, CCNB1, DLGAP5, and NCAPG were upregulated in tumor tissue compared with normal tissue." (PMID 36250027, 2022). "AURKA primarily matched Aurora A inhibitors such as TAS-119, MK-5108, and SNS-314, which inhibit tumor growth by inducing apoptosis." (PMID 35370655, 2022). "Studies have also reported that p27 inhibited promoter transcription of target genes, such as AURKA and MED18, which are closely related to the poor tumor prognosis." (PMID 34617876, 2021). "More importantly, both WT and mutant NKX3.1 completely inhibited chemotaxis, underscoring a major tumor-suppressive role of NKX3.1, one of which includes degrading AURKA." (PMID 34625072, 2021). "AURKA is an important member of the AURK kinase family, which is involved in the occurrence of various tumors and is closely related to tumor prognosis." (PMID 34539737, 2021). "AURKA also plays a central role in the progression of solid tumors through activation of EMT and tumor stemness." (PMID 33674749, 2021). "Taken together, these findings reveal for the first time the critical role of AURKA oncogenic signaling in mediating TGF-β-induced TNBC plasticity, chemoresistance, and tumor progression." (PMID 33674749, 2021). "Remarkable, a combination of galunisertib (TGF-β inhibitor), alisertib (AURKA inhibitor), and DTX inhibited tumor relapse and organ metastatic burden." (PMID 33674749, 2021). "Our previous work has identified the tumor suppressors BRCA1 and CHK2 and the oncogenic kinase AURKA as regulators of mitotic microtubule growth rates and for W-CIN." (PMID 33168930, 2021). "We found that four of the hub genes (TOP2A, AURKA, NEK2, and RACGAP1) can serve as tumor therapeutic targets for drugs approved by FDA." (PMID 33946043, 2021).
tumor (continued). "Since the hub genes in the IPA network were AURKA and EZH2, we further validated the role of AURKA and EZH2 in tumor cell proliferation and migration in HCC cell lines." (PMID 35059393, 2021). "While these clinical studies supported a potential role for AURKA inhibition in the management of patients with advanced NB, patients with MYCN/MYC-driven tumours still showed poor outcomes despite treatment with this regimen." (PMID 34195095, 2021). "AURKA also stabilizes the transcription factor N-MYC, thereby promoting G1/S cell cycle transition and tumor cell proliferation." (PMID 34332577, 2021). "For further exploration, we conducted an integrated analysis to predict the potential biological roles of AURKA and FAM83A in tumor-immune of LUAD." (PMID 33613763, 2021). "Another AURKA inhibitor, namely PHA-739358, suppress proliferation of human SHH MB models, including allografts of Patched mutant tumour cells and patient-derived xenografts." (PMID 34195095, 2021). "Inhibition of AURKA and the PI3K/mTOR pathway using alisertib and NVP-BEZ235, respectively reduced tumor burden in a 786-0 xenograft model of RCC." (PMID 34002003, 2021). "The result of q-rtPCR showed that the mRNA expression levels of PTGS2, RRM2, AURKA, CAV1, MAP3K5, STEAPS are higher in tumor samples and lower in normal tissue samples and the others had the reverse tendency." (PMID 33819918, 2021). "AURKA levels were also significantly higher in local and metastatic CRPC tumor specimens as compared to hormone-naïve PCa samples." (PMID 34625072, 2021). "Mechanistically, we further explore the correlation between AURKA and FAM83A gene expression levels and tumor-infiltrating lymphocytes (TILs) level as well as their response to immunomodulators." (PMID 33613763, 2021). "Results showed that four of these hub proteins (AURKA, CDC45, ESPL1, and RAD54L) were over-expressed in all tumor subtypes." (PMID 32932728, 2020). "Aurora kinase A (AURKA) is a protein that regulates centromere and cell mitosis, affecting the progression of several neoplasms." (PMID 33050100, 2020). "While AURKA is a well-established oncogene, SPOP can act as a tumor-promoter or tumor-suppressor depending on the cell type." (PMID 33158056, 2020). "Further clinical validation of the tumor promoter and worse prognosis predictor function of NDC80 and MAD2L1 in local LUAD and LUSC patients as well as the genes’ relation with BUB1B and AURKA is on our way." (PMID 32795325, 2020). "We here find that CEP41 facilitates hypoxia‐induced angiogenesis through HIF1α‐AURKA‐VEGF pathway in vitro and further show that CEP41 affects EC dynamics under tumor‐induced hypoxic conditions in vivo." (PMID 31885126, 2020). "AURKA overexpression was also suggested to increase the expression of MMP-2, MMP-7, MMP-9, leading to tumor metastasis by degrading extracellular matrix proteins." (PMID 33245732, 2020). "AURKA and PLK1 expression levels are elevated in tumor tissues compared to adjacent normal tissues in patients with HCC." (PMID 31214512, 2019). "In contrast, the expression of GGI-GS, DiLeoRBloss-GS, Rbloss-GS, CIN70-GS, E2FmotifCellCycleAssociated-GS, Gene70-GS, E2F4activation-GS, AURKA-GS, PTEN-GS, E2Factivation-GS, and IGF1-GS were significantly higher in the noCCCA tumours (all p < 0.0001)." (PMID 31892336, 2019). "Pharmacological inhibition of AURKA and PAK1 synergistically decreased survival of multiple tumor cell lines, showing particular effectiveness in luminal and HER2-enriched models, and inhibited growth and ERα-driven signaling in a BT474 xenograft model." (PMID 31254157, 2019). "AURKA is overexpressed in SNF5 mutant rhabdoid tumors, and AURKA silencing sensitized the tumor cells to apoptosis induction." (PMID 30097580, 2018).
tumor (continued). "Transcriptomic analysis of the tumor has shown upregulation of various oncologically relevant pathways, including EGF/ErbB, Aurora Kinase A, pak21 and wnt." (PMID 29535801, 2018). "We have previously demonstrated that in primary FLC tumor tissue there are consistent changes in various oncologically relevant pathways such as EGF/ErbB2, Aurora Kinase A and wnt signaling pathways." (PMID 29535801, 2018). "However, whether AURKA involves in tumor local invasion remains elusive." (PMID 28592839, 2017). "In another study, the tumor suppressor SIRT2 has been found to interact with and degrade AURKA, partially accounting for the observation that Sirt2-deficient male mice would develop more HCC than wild-type mice." (PMID 28903390, 2017). "We observed that high levels of AURKA were a marker of poor prognosis in both tumour types, highlighting a clinical role for this kinase in KRAS-driven tumours." (PMID 28220783, 2017). "Because many of the substrates that FBXW7 targets for degradation are well-known oncoproteins, such as Cyclin E, c-Myc, Aurora kinase A (AURKA) and Notch-1, FBXW7 is generally accepted as a tumor suppressor." (PMID 27409838, 2016). "Results from previous studies have suggested that the overexpression of AURKA increases the level of p-GSK-3β, p-Akt1 and β-catenin and plays an important role in cell proliferation, tumor progression and metastasis." (PMID 27121204, 2016). "The RT‐PCR data confirmed a strong correlation of AURKA and RACGAP1 gene expression both in the tumor, the tumor‐adjacent and the tumor‐distant mucosa." (PMID 26778597, 2016). "Univariate analysis showed that the OS of all 99 patients was also significantly influenced by age, ECOG performance status, tumor size, platelet count, AST level, AURKA expression level, and treatment response in addition to albumin and sodium levels." (PMID 24901229, 2014). "Luminal B tumours have a worse prognosis than Luminal A tumours and can be identified by the high expression of specific proliferation-related genes such as KI67 or Aurora A kinase (AURKA)." (PMID 25472026, 2014). "Univariate analysis showed that the PFS of all 99 patients was significantly influenced by age, ECOG performance status, tumor size, platelet count, aspartate aminotransferase (AST) level, AURKA expression level, and treatment response." (PMID 24901229, 2014). "Collectively, our data indicate that AURKA is a rationale therapeutic target for MPNST and tumour cell responses to AKI, which include differentiation, are modulated by the abundance of HMMR/RHAMM." (PMID 23328114, 2013). "We used a meta-analysis based on seven data sets and found CEI1 was negatively correlated with ER/luminal-basal metagenes and ERBB2-molecular apocrine tumor metagenes; whereas CEI3 was positively correlated with the proliferation/AURKA metagene." (PMID 21798043, 2011). "In the present study we evaluated AURKA expression in NSCLC showing that at both transcript and protein levels, the AURKA expression was significantly up-modulated in NSCLC tumor samples compared to matched lung normal tissue (p < 0.01, mean log2(FC) = 1.5)." (PMID 21718475, 2011). "Mindful of the suggestion of Keen and Taylor (2004) that AURKA and AURKB were generally coordinately expressed in human tumours, we analysed the expression levels of AURKA in the 30 patient series analysed for genetic instability by real time quantitative PCR." (PMID 16222316, 2005). "Our findings suggest that AURKA may represent a potential therapeutic target, particularly in HBV-HCC and Cr-HCC, tumor subtypes characterized by genomic instability and dysregulated mitotic control." (PMID 41515655, 2026). "However, the activity of AURKA on its downstream substrates (P53Ser315, PLK1Thr210, and BRCA1) differed between the two tumor groups." (PMID 41515655, 2026).
tumor (continued). "We investigated the HPA immunohistochemistry and DepMap CRISPR screenings to confirm the tumor-intrinsic essentiality of PLK1 and AURKA, while utilizing the TISCH single-cell dataset to validate the microenvironmental specificity of CTLA4 (T-cells) and PPARG (CAFs/Macrophages)." (PMID 41596281, 2026). "Key mitotic regulators, including kinases such as PLK1, AURKA, AURKB, and MPS1 and kinesins such as CENPE and Eg5, are frequently overexpressed in NSCLC and SCLC, contributing to chromosomal instability, aneuploidy, and highly proliferative tumor phenotypes." (PMID 42076055, 2026). "AURKA exhibited both CNV amplification and SV abnormalities in READ and OV, suggesting that its genomic instability may be related to specific tumor microenvironments." (PMID 40718709, 2025). "Furthermore, AURKA induces epithelial-mesenchymal transition (EMT) and promotes tumor cell migration and invasion by activating signaling pathways such as PI3K/AKT and Wnt/β-catenin." (PMID 40718709, 2025). "CDC20, AURKA, and CCNF are highly expressed in a variety of tumor cell lines." (PMID 39895786, 2025). "However, AURKA is also known to be upregulated by HPV E7, which increases tumour cell proliferation." (PMID 39518152, 2024). "In addition, structural stabilization of N-Myc proteins mediated by AURKA further upregulated VEGF expression in NB and promoted intra-tumor angiogenesis." (PMID 39585848, 2024). "Another study found that cinobufagin can inhibit the AURKA-mTOR-eukaryotic translation initiation factor 4E (EIF4E) signaling pathway, and block the formation of the spindle body in Huh-7 cells, thereby exerting an anti-tumor effect." (PMID 38803433, 2024). "Finally, the subcutaneous tumor formation experiments in nude mice using the H1975 wildtype and KEAP1-knockdown cells further confirmed that the sensitivity of NSCLC cells to the AURKA inhibitor MLN8237 was significantly enhanced after KEAP1 knockdown." (PMID 38521813, 2024). "We observed in tumour samples that AURKA inhibition does not influence the expression and phosphorylation levels of LATS-1 and MOB-1, main effectors of the Hippo-dependent YAP1 phosphorylation at Ser397." (PMID 38467828, 2024). "Consistently, tumour cells carrying PP6 mutations and lacking PP6 catalytic activity display increased activity (by 200%) of AurkA in the complex with TPX2." (PMID 39195284, 2024). "The AurkA/TPX2 complex is overexpressed in several tumour types (breast, lung, prostate, ovarian, and others) and contributes to aneuploidy as well as CIN, favouring tumour heterogeneity and drug resistance." (PMID 39195284, 2024). "The regulatory landscape of circRNAs-AURKA in HCC is less studied compared to miRNAs and lncRNAs, even though accumulating evidence has demonstrated that the dysregulation of circRNAs plays a pivotal role in tumor development and progression." (PMID 39598228, 2024). "As a cell cycle regulator, AURKA's role in promoting proliferation is not surprising, and its dysregulation can lead to aneuploidy and tumour development." (PMID 38590119, 2024). "Our study unveiled AURKA’s relationships with immune and ESTIMATE scores, as well as various immune cells and immune-related regulatory genes, emphasizing its close ties to immune cell infiltration within the tumor microenvironment." (PMID 37965456, 2023). "In this study, we describe for the first time a molecular mechanism involving the dysregulation of APA and the differential targeting of AURKA APA isoforms by hsa-let-7a, a tumor suppressor miRNA, that is sufficient for the oncogenic activation of AURKA at the post-transcriptional level." (PMID 37384380, 2023). "However, alisertib plus T/CQ elicited tumor regression, suggesting that reducing the c-MYC expression by AURKA blockade conferred sensitivity to T/CQ therapy." (PMID 36719686, 2023).
tumor (continued). "However, emerging evidence suggests that AURKA also mediates resistance to CDK4/6 inhibitors in vitro and in tumor samples." (PMID 37760421, 2023). "Moreover, the expression of SNHG4, TK1, AURKA, RRM2 and EZH2 in the tumor tissues was found to be significantly elevated after SNHG4 overexpression." (PMID 37596700, 2023). "After the detection of hub genes utilizing the PPI network of common upregulated genes, the top five hub genes, including AURKA, AURKB, KIF20A, MELK, and TTK that played the most critical role in both primary tumor cell and P7731 cell line, were selected to validate the study." (PMID 37231064, 2023). "Another TNBC case, PDXBC9, was associated with a high response to targeted therapies such as HSP90 and AURKA inhibitors, yet this tumor carried no known molecular alterations in the HSP90 or AURKA pathways." (PMID 37377606, 2023). "In addition, the expressions of genes involved in tumor suppression (PTEN), cell growth inhibition (AURKA), and apoptosis (BIM and Bcl-2) have been measured in cells exposed to OEO." (PMID 36678556, 2022). "Moreover, six paired fresh tumor tissues and paraneoplastic tissues from children with MRTK were collected to validate the expressions of P4HA1, MLLT11, AURKA, and GOT1 in clinical samples via real-time fluorescence quantitative PCR and Western blot." (PMID 35558559, 2022). "Compared with a continuous increase of hub gene expression in normal to SILs to SCC transitions, only AURKA mRNA expression significantly increased with advancing FIGO stage, increasing tumor differentiation and aggressiveness in SCC, as indicated by the poor OS." (PMID 36352434, 2022). "Considering the interactions of MAP9 with Plk1 and AURKA, we hypothesized that MAP9 is vital in tumor progression." (PMID 35656338, 2022). "Due to the small size of the tumor and very limited tumor tissue available at 1st relapse we did not test the relapsed tumor for AURKA expression or methylation studies." (PMID 35967099, 2022). "Moreover, enhanced CLIP (eCLIP) was used to validate that AURKA mRNA is a direct target of IGF2 mRNA-Binding Protein 1 (IGF2BP1), an important tumour and stem cell fate regulator, and is stabilized by IGF2BP1 binding." (PMID 36067794, 2022). "For tumour cell migration, AURKA induces the expression of SLUG, FNB1, and MMP and activates signalling pathways that promote tumour cell migration, including AKT, MAPK, cofilin-F-actin, SRC, and MCAK, to promote tumour cell migration." (PMID 36471438, 2022). "In addition, inhibition of AURKA was shown to result in a significant reduction of GPX4 and induction of ferroptosis in tumor cells." (PMID 36072667, 2022). "PTPRD has also other relevant targets, such as aurora kinase A (AURKA), which may also mediate its tumor suppressive functions." (PMID 35982066, 2022). "Hence, it has been shown that different genes such as P16, AURKA, and AURKB play an important role in tumor growth in ATC." (PMID 36482411, 2022). "Immuno-histochemistry for INI1 (BT Transduction Laboratories, clone 25/BAF47, 1:200) and AURKA (Abcam, clone EP1008Y, 1:100) was performed on deparaffinized sections from the tumor sample at diagnosis in a CLIA approved lab (St Jude Children’s Research Hospital, B.A.O.)." (PMID 35967099, 2022). "In addition, the expression of the cell proliferation markers AURKA, AURKB, CCNB1, and MKI67 was higher in the patients’ tumor tissues than those of normal tissues." (PMID 34503223, 2021). "Functional analyses and a mouse xenograft-tumor model also showed that knockdown of SOCS2-AS1 markedly induced EC cell proliferation and that this effect was completely rescued by simultaneous knockdown of both SOCS2-AS1 and AURKA." (PMID 33824269, 2021).